CDH1 (cadherin 1)
Diseases named in the same sentence as CDH1 in open-access papers (continued):
Sharing a sentence is not in itself a finding about the gene and the disease.
osteosarcoma (88 papers, 2013 to 2025). A usually aggressive malignant bone-forming mesenchymal neoplasm, predominantly affecting adolescents and young adults. "Increased interaction between BRD7 and cdh1 or cdc20 leads to ubiquitin-mediated degradation of BRD7 in osteosarcoma." (PMID 32992509, 2020). "In this study, we found that APC/Ccdh1 and APC/Ccdc20 directly bind and degrade BRD7, a finding that is clinically relevant because a strong inverse correlation between the expression levels of BRD7 and Cdh1 or Cdc20 was observed in patients with osteosarcoma." (PMID 24840027, 2014). "Both Cdh1 and Cdc20 were mainly located in the nuclei of osteosarcoma cells, consistent with the reports showing that the tumor cells exhibited positive nuclear staining of Cdh1 or Cdc20." (PMID 24840027, 2014). "Importantly, the BRD7 protein levels are inversely correlated with Cdh1 or Cdc20 protein levels in osteosarcoma clinical samples." (PMID 24840027, 2014). "The acetylation status of Cdh1 or Cdc20 in osteosarcoma may be different from that in other cancer cell types, a topic that deserves future investigation." (PMID 24840027, 2014). "In a dose- and time-dependent manner, MTF inhibited proliferation, migration and invasion of osteosarcoma cells and this effect was associated with decreased expression of phosphorylated AKT serine/threonine kinase 1 (p-Akt) and vimentin (VIM), and increased expression of PTEN and cadherin 1 (CDH1)." (PMID 30241339, 2018). "Future studies will focus on the possible CtBP1 dependence of the downregulation of CDH1, BAX, BIM, and PTEN in osteosarcoma CSCs." (PMID 33391445, 2021). "These included CDH1-Blepharocheilodontic (BCD) Syndrome, CHEK2-osteosarcoma, NF1-leukemia, and NF1-pulmonary stenosis." (PMID 33959510, 2021). "In human osteosarcoma tissues, the anaphase-promoting complex/cyclosome (APC/C), a complex of E3 ligases that mediates the ubiquitination of proteins during mitosis, targets BRD7 for ubiquitin-mediated degradation through its co-activators cdh1 and cdc20." (PMID 32992509, 2020). "Furthermore, there is a strong inverse correlation of protein levels between BRD7 and Cdh1 or Cdc20, and lower BRD7 expression is an indicator for poor prognosis in patients with osteosarcoma." (PMID 24840027, 2014). "Furthermore, an inverse correlation was observed between the protein levels of BRD7 and Cdh1 or Cdc20 (p<0.001, χ2 tests), demonstrating that Cdh1 and Cdc20 may also negatively regulate BRD7 protein in osteosarcoma tissues." (PMID 24840027, 2014). "The CtBP1-p300-FOXO3a complex can specifically repress the expression of two downstream targets, Bax and Bim, but not other known CtBP1 targets such as CDH1 (epithelial Cadherin), PTEN (Phosphatase and Tensin Homolog), and CDKN1A (Cyclin-Dependent Kinase Inhibitor 1A) in human osteosarcoma cells." (PMID 31754335, 2019).
glioblastoma (84 papers, 1995 to 2025). The most malignant astrocytic tumor (WHO grade IV). "A similar oncogenic effect is caused by the E-cadherin variant encoded by the circE-Cad at the CDH1 gene (C-E-Cad- 254aa), involved in the maintenance of the cancer stemness in glioblastoma by interacting with EGFR and activating downstream STAT3 signaling." (PMID 37587333, 2023). "Glioblastoma CSCs have been noted to exhibit diminished APC/C-Cdh1 activity as a result of hyperphosphorylated Cdh1 affecting complex formation." (PMID 34831136, 2021). "Since no SOX2-targeting E3 ubiquitin ligase has yet been identified in glioblastoma cells, we tested the role of four E3 ubiquitin ligases (CDH1-APC, CUL4A, UBR5, and WWP2) which have been demonstrated to target SOX2 in other cellular contexts through an RNA interference-based approach in GSCs29–32." (PMID 34732716, 2021). "The study aimed to determine the expression of carcinogenesis-related SLC5A8, SLC12A2, SLC12A5, CDH1, and CDH2 in adult glioblastoma U87 MG and T98G cells and the effects of 0.5 mM, 0.75 mM, and 1.5 mM doses of VPA." (PMID 39061990, 2024). "This study aimed to investigate the effect of VPA on the expression of the NKCC1, KCC2, and SLC5A8 co-transporters genes and the CDH1 and CDH2 genes in adult glioblastoma U87 MG (female) and T98G (male) cells." (PMID 39061990, 2024). "Background/Objectives: The study aimed to determine the expression of carcinogenesis-related genes, such as SLC12A2, SLC12A5, CDH1, CDH2, EZH2, and GFAP, in primary glioblastoma (WHO Grade IV; IDH-wild-type) cells from three adult women: GBM5-1, GBM5-2F, and GBM5-3F." (PMID 41012498, 2025).
invasive ductal carcinoma (84 papers, 1996 to 2025). "The patient in whom a pathogenic variant in CDH1 was identified had been diagnosed with invasive ductal breast carcinoma." (PMID 31125277, 2019). "However, recent studies showed that 21% of invasive ductal carcinomas also exhibited the CN loss of CDH1 and 27% of high-grade invasive ductal carcinomas exhibited reduced or loss of E-cadherin membranous expression." (PMID 39049123, 2024). "On the contrary, invasive ductal breast carcinomas rarely harbor CDH1-inactivating mutations." (PMID 33808143, 2021). "Patients with A allele of CDH1 -160 C/A was in higher risk to progress invasive ductal carcinoma." (PMID 29285016, 2017). "In this work, E-cadherin gene (Cdh1) was depleted in MMTV-PyMT invasive ductal carcinoma cells and as expected, this resulted in increased invasion." (PMID 31783547, 2019). "Loss of 16q, where potential tumor suppressor genes such as E-cadherin (CDH1) and CDH13 are located, is also known to be a major event in low-grade invasive ductal carcinoma." (PMID 22938721, 2012). "In this sense, it has been reported that more than two third of mixed ductal-lobular carcinomas do not have CDH1 mutations and their mutational and transcriptional profiles are suggestive of invasive ductal carcinoma." (PMID 30153845, 2018). "While immunohistochemical studies have demonstrated that reduced or absent E-cadherin expression is also common in infiltrating ductal carcinomas (IDCs), in the majority of these cases, CDH1 mutations were rare or absent." (PMID 16512896, 2006). "Interestingly, invasive ductal carcinomas with 16q-disomy (CTRL, B2, and C) showed a higher level of CDH1 transcripts in comparison to normal breast tissues, while CDH1 levels in invasive ductal carcinomas with 16q-loss (group A, B1, and D) were similar to those of normal tissue." (PMID 33808143, 2021).
pulmonary fibrosis (82 papers, 2013 to 2026). Chronic progressive interstitial lung disorder characterized by the replacement of the lung tissue by connective tissue, leading to progressive dyspnea, respiratory failure, or right heart failure. "CDH1 or E cadherin is an epithelial cell adhesion molecule that regulates cell differentiation and morphogenesis, and is associated with lung fibrosis and cancer." (PMID 25306249, 2014). "In comparison to the neutrophilic cases, the IPA analysis of the proteomic datasets derived from horses with metachromatic inflammation revealed enrichment in pathways related to hypersensitivity reaction (CD44, ICAM1, SOD1, PSAP, CDH1) and lung fibrosis (AGER, TGFBR2, FBLN1, S100A9)." (PMID 39594673, 2024). "For example, CDH1, a classical cadherin of the cadherin superfamily, was found downregulated severely, indicating the patients with COVID-19 may develop pulmonary fibrosis." (PMID 33060566, 2020). "Thus, it is necessary to determine whether SIRT1, Cdh1, and AROS are functionally associated with pulmonary fibrosis." (PMID 37258580, 2023). "Overall, our results suggest opposing roles for Cdh1 and AROS in SIRT1 degradation during the development of pulmonary fibrosis and support pinosylvin as a therapeutic agent for human pulmonary fibrosis." (PMID 37258580, 2023).
colitis (80 papers, 2010 to 2025). Inflammation of the colon. "In IBD, MAGI2, GNAI2, MIO9B, PTPN2, and CDH1 genes have been identified as tight junction assembly and barrier function regulators and were significantly associated with colitis." (PMID 33806347, 2021). "Finally, the intestinal permeability was investigated, showing an increased permeability for 4 kDa FITC-dextran in colitis mice associated with a decreased mRNA level of junctional proteins Cldn1, Cldn2, Cdh1 and Ocln and an unaltered expression of scaffolding protein Zo1." (PMID 34248633, 2021). "We first found that both WT mice and Cdh1 mutant mice develop very heavy colitis in the later stages of DSS-induced colitis." (PMID 39250508, 2024). "The aim of this study was to evaluate the role of the human native bacterial strain L. gasseri ATCC33323 in a DSS-induced murine model of colitis and to apply mouse hybridization to construct transgenic mice with semiknockout of the intestinal Cdh1 gene." (PMID 39250508, 2024). "During the DSS modeling period, the mice in the CDH1+/- DSS group presented early colitis symptoms and died early, while the mice in the NC LAB group presented the highest survival rate." (PMID 39250508, 2024). "Here, treatment with UAMC-00050 had a small but significant effect on the permeability towards 4 kDa FITC-dextran and also reduced the mRNA expression levels of Cdh1 and Ocln in T cell transfer colitis mice." (PMID 34248633, 2021). "Furthermore, UAMC-00050 fairly but significantly lowered the Cdh1 expression level in colitis mice and the Ocln expression level in both control and colitis mice without having any effects on the mRNA level of any other junctional proteins in colitis or control mice." (PMID 34248633, 2021). "On the fifth day after DSS induction, the DAI was greater in the CDH1+/- DSS group than in the NC DSS group (P<0.05), demonstrating that the absence of E-cadherin in the intestine accelerated the progression of colitis." (PMID 39250508, 2024). "Expression of Cldn3, Cldn4, Cldn7 and Cdh1 mRNA was however not altered during colitis or due to the absence of Muc13 expression in mice." (PMID 37174625, 2023). "In mice model of colitis, resveratrol, diet with red raspberries powder (rich in insoluble fiber), and dietary CLA (conjugated linolenic acid) administration upregulated tight junction proteins E-cadherin 1, ZO-1, CLDN3 and OCCL gene expressions." (PMID 33806347, 2021). "Moreover, colitis symptoms and colon shortening can be significantly alleviated in WT mice following L. gasseri ATCC33323 intervention, whereas L. gasseri ATCC33323 does not have a good therapeutic effect on Cdh1 mutant mice." (PMID 39250508, 2024).
thyroid cancer (80 papers, 2005 to 2026). "Notably, the epigenetic downregulation of CDH1 is associated with increased invasiveness of thyroid cancer cells in vitro and the suppression of E‐cadherin in lymph node metastases of papillary thyroid cancer." (PMID 38374872, 2024). "Taken together, our findings showed that promoter methylation of the CDH1 gene played an important role in thyroid cancer initiation and progression." (PMID 28926589, 2017). "E-Cadherin (CDH1) expression is reduced in thyroid carcinomas and its promoter resulted to be hypermethylated in thyroid neoplasm." (PMID 22958914, 2012). "Notably, enhanced invasiveness of thyroid cancer cells in vitro and the suppression of E-cadherin in lymph node metastases of papillary thyroid carcinoma are linked to the epigenetic downregulation of CDH1." (PMID 40581650, 2025). "However, in colon adenocarcinoma, renal clear cell and papillary cell carcinoma, and thyroid carcinoma, CDH1 was significantly decreased." (PMID 36131343, 2022). "By immunohistochemistry several transcription factors implicated in EMT induction, such as SLUG (SNAI2), TWIST1 and ZEB1 are all up-regulated in ATC compared to normal thyroid and well-differentiated thyroid cancers and coordinately act to repress E-cadherin (CDH1) expression." (PMID 29383121, 2017). "Furthermore, during the metastatic progression of PTC (papillary thyroid cancer) the dynamic changes of CDH1 epigenetic silencing are functionally related with the in vitro thyroid cancer cell invasiveness the in vivo E-cadherin downregulation in lymph nodal metastases." (PMID 32806509, 2020). "Epigenetic heterogeneity is found in four (CDH1, AP2, HIN1, and DACT2) of the five detected genes in thyroid cancer." (PMID 34539742, 2021). "Five genes (AP2, CDH1, DACT2, HIN1, and RASSF1A) are found frequently methylated (>30%) in thyroid cancer." (PMID 34539742, 2021). "In a panel of analyzed tumor suppressors, promoter hypermethylation of CDH1, p16INK4A, RASSF1A and SLC5A8 in malignant thyroid tumors was confirmed." (PMID 25490036, 2014). "For genes previously reported to be methylated in thyroid cancer, such as TSHR, or in other cancer types, such as RASSF1A, RAR-β2, p16, CDH1, DAPK, and MLH1, the methylation frequency in papillary thyroid cancer ranges from 15 to 33%." (PMID 24367375, 2013). "Five genes (AP2, CDH1, DACT2, HIN1, and RASSF1A) are methylated more than 30% in thyroid cancer." (PMID 34539742, 2021).
triple-negative breast carcinoma (77 papers, 2010 to 2026). An invasive breast carcinoma which is negative for expression of estrogen receptor (ER), progesterone receptor (PR), and human epidermal growth factor receptor 2 (HER2). "CDH1 deficiency is common in diffuse gastric cancer and triple negative breast cancer patients, both of which still lack effective therapeutics." (PMID 37324948, 2023). "Treatment of triple negative breast cancer cells with dasatinib led to reduced p-Y148-Cdh1 while PD0325901 suppressed serine/threonine phosphorylation of Cdh1." (PMID 31420536, 2019). "MDA-MB-231 cells, a highly proliferative phenotype and an E-cadherin-negative triple-negative breast cancer cell line, typically exhibit low CDH1 expression." (PMID 40558895, 2025). "Studies have elucidated that the reduction of CDH1 expression increases the cytotoxic effect of PARPi on triple-negative breast cancer cells with or without BRCA defects by inducing DNA damage, checkpoint activation, cell cycle arrest, and cell apoptosis." (PMID 39009979, 2024). "Here we demonstrate that the tumor suppressive miRNA family, miR-200, is not expressed in triple negative breast cancer (TNBC) cell lines and that miR-200b-3p over-expression represses EMT, which is evident through decreased migration and increased CDH1 expression." (PMID 26062653, 2015).
adenoma (64 papers, 2008 to 2025). A neoplasm arising from the epithelium. "Previous studies from the United States suggest CDH1 variant carriers have an increased risk for adenomas or sessile serrated lesions (SSL), yet data linking CDH1 PVs and colorectal neoplasia are scarce." (PMID 40323501, 2025). "Combined conditional loss of Cdh1 and Apc were generated in the intestine, intestinal adenoma and adenoma organoids." (PMID 27566565, 2016). "Adenoma organoid cultures derived directly from adenoma tissue in vivo, where alleles were recombined (e.g. PCR positive for ApcΔ/Δ), were then genetically complemented with Cdh1 expressed using adenoviral expression vectors, and phenotypes evaluated." (PMID 27566565, 2016). "Our initial results suggested that Cdh1 heterozygosity might promote Apc loss of function induced adenoma formation." (PMID 27566565, 2016). "Two, 85 patient studies from the United States reported adenomas and sessile serrated lesions in 41–47% of CDH1 PV carriers undergoing colonoscopy, including 27-50% under age 45 years at time of the examination." (PMID 40323501, 2025). "The possible increased risk of CRC in this population is consistent with the occurrence of early-onset CRC in 2 of the 3 CDH1 PV carriers diagnosed and the detection of advanced adenomas/SSLs in the age group below 45 years." (PMID 40323501, 2025). "This first international study provides preliminary evidence of a higher ADR in U.S. CDH1 PV carriers compared to the general population, with a high number of adenomas detected before the age of 50." (PMID 40323501, 2025). "The expression levels of Pax8, Cdh1 and Muc16 trended to be higher in both the sex cords and adenoma samples, as compared to the naïve and mature GC controls." (PMID 37174061, 2023). "Whereas CDH1 expression was gradually decreased in primary tumor and metastasis specimens compared with adenoma and normal samples, the opposite was true for VIM expression." (PMID 36834820, 2023). "The expression of Pax8 was significantly higher in sex cords versus mature GCs (p = 0.029), and Cdh1 (p = 0.017) expression was significantly higher in the adenoma compared to all other phenotype groups." (PMID 37174061, 2023). "After induction of dominant negative E-cadherin or inactivation of the Cdh1 gene, massive formation of blood and lymph vessels, termed the "angiogenic switch" was observed in the adenomas." (PMID 18492263, 2008). "For module yellow, which is progressively up-regulated from normal stroma to adenoma to mCA, the top candidate hub genes consisted of CDH1, ST14, EHF, KRT8, and KIAA1217, all of which have important roles in epithelial cells, and/or are associated with tumour malignancy." (PMID 32218455, 2020). "Loss of Cadherin 1 (CDH1), a glycoprotein responsible for calcium-dependent cell-to-cell adhesion, can also induced EMT, and its downregulation is associated with tumor grade and stage and contributes to the transition of adenoma to carcinoma in animal models." (PMID 29262659, 2017). "Genotyping of adenoma showed most retained Cdh1 non-recombined (Cdh1fl/fl) alleles, with a minority of adenoma showing evidence of recombination by PCR, although similar detectable Cdh1 mRNA expression was seen irrespective of genotype." (PMID 27566565, 2016). "Co-infection of ApcΔ/ΔCdh1fl/flLgr5CreERT2 adenoma cells with a CMV promoter driven adenovirus expressing either murine wild-type or an EC1 domain mutated Cdh1 cDNA, were combined in vectors with an IRES for the fluorescent reporter RFP (Ad-Cdh1-WT-RFP or Ad-Cdh1-Mut-RFP)." (PMID 27566565, 2016). "By co-infecting ApcΔ/ΔCdh1fl/flLgr5CreERT2 adenoma cells with Ad-Cre-GFP combined with either Ad-Cdh1-WT-RFP or Ad-Cdh1-Mut-RFP, we tested the effects of double transfection with Cre and Cdh1 expressing viruses." (PMID 27566565, 2016).
adenoma (continued). "The overall adenoma detection rate (ADR) was 35.9% (95% CI:27.3–45.5%), with surveillance being the indication in most cases (88.2%), representing the first pan-continental data on ADR in CDH1 PV carriers." (PMID 40323501, 2025). "Of the surviving cohort of Cdh1fl/flVil-CreERT2 treated with low dose tamoxifen and aged to one year, neither adenoma nor tumors formed (Cdh1fl/flVil-CreERT2 n=4, Cdh1+/flVil-CreERT2 n=6, Cdh1+/+Vil-CreERT2 n=3)." (PMID 27566565, 2016). "Adenomas with positive Snail1 nuclear immunostaining had a lower level of CDH1 mRNA and with absent nuclear Snail1 staining showed higher levels of CDH1 mRNA." (PMID 23029563, 2012). "We addressed the functional consequences of weakening or destroying cell-to-cell adhesion in the adenomas of SP-C C-RAF BXB mice using two different genetic approaches, conditional ablation of the Cdh1 gene in mice with a "floxed" Cdh1 gene or switchable expression of dominant negative E-cadherin." (PMID 18492263, 2008).